FABP4 (fatty acid binding protein 4)
Diseases named in the same sentence as FABP4 in open-access papers (continued):
Sharing a sentence is not in itself a finding about the gene and the disease.
metabolic syndrome (continued). "FABP4, as a bridge between the inflammation and other metabolism syndromes, could not only transport the nuclear receptor PPAR-γ from cytoplasm to nucleus but also cause increased transcript activation of it." (PMID 19638242, 2009). "Notably, the association between chronic coronary syndrome and FABP4 persisted after adjusting for dyslipidemia with statin use, suggesting that low FABP4 levels may still serve as a useful predictor in treated patients." (PMID 41187309, 2025). "Notably, the FABP4 level predicted future CVDs independent of traditional risk factors including obesity and dyslipidemia." (PMID 39725654, 2024). "Thus, hepatic Fabp4 may be an important factor in high-fat diet induced metabolic syndrome and subsequent atherosclerotic disease." (PMID 38698167, 2024). "Serum FABP4 levels were positively associated with suspected liver steatosis assessed by the fatty liver index (FLI) in both normal glucose tolerance subjects and patients at increased cardiometabolic risk, including diabetic, obese, and metabolic syndrome patients." (PMID 35052876, 2022). "In addition, recent observations have also demonstrated that the concentration of FABP4 could be altered by administering therapeutic drugs for HT, dyslipidemia and DM." (PMID 33503066, 2021). "FABP4 is a direct target gene of PPARγ, and has been shown to activate multiple metabolic and inflammatory signal pathways in both adipocytes and macrophages, thus plays a critical role in insulin resistance, type 2 diabetes, atherosclerosis and other metabolic syndromes." (PMID 27294862, 2016). "Thus, increased FABP4, adipsin and adiponectin in colitic epithelial Paneth cells may be involved in the occurrence and development of metabolic syndrome." (PMID 26687459, 2015). "mRNA of fatty acid binding protein 4 (FABP4)—which is a strong biomarker of HIV, generated metabolic syndrome and lipodystrophy—was significantly upregulated by HIV-2 but not by HIV-1 even at later time-points." (PMID 38203551, 2023). "The regulation of FABP4, adiponectin, and adipsin by L. taiwanensis strain BCRC 17755 in Paneth cells provided a clue to reveal the relationship between the metabolic syndrome and gut microbiota." (PMID 36557581, 2022). "Serum FABP4 positively correlated with FLI in the whole population as well as in diabetic, obese, and metabolic syndrome patients." (PMID 34966292, 2021). "Moreover, serum FABP4 levels were shown to be significantly the highest in the GDM group in the early puerperium, which may suggest that elevated FABP4 levels may persist in GDM patients postpartum and contribute to increased risk of T2DM and metabolic syndrome." (PMID 34769010, 2021). "However, circulating FABP5, similar to FABP4, has been reported to be detected at levels of about one tenth or less of FABP4 concentrations, and FABP5 level has been shown to be associated with components of metabolic syndrome, though the correlation is not as strong as that of FABP4." (PMID 27936164, 2016). "Secondly, as far as we surveyed, a relationship between FABP5 and UPR has not been identified, although FABP4, which is a critical indicator for various metabolic syndromes as is FABP5, has been shown to be importantly involved in UPR." (PMID 39273233, 2024). "Serum FABP4 was positively related with liver steatosis in the whole population, in diabetic and metabolic syndrome, but not in obese patients in the crude model." (PMID 34966292, 2021). "Serum FABP4 levels positively correlated to FLI in the whole population (ρ = 0.387, P < 0.001), diabetic (ρ = 0.444, P < 0.001), obese (ρ = 0.392, P < 0.001), and metabolic syndrome (ρ = 0.300, P < 0.001) patients." (PMID 34966292, 2021). "Therefore, serum FABP4 level may be a discriminative marker for predicting PCOS and subsequent metabolic syndrome." (PMID 37628833, 2023).
metabolic syndrome (continued). "Additionally, serum FABP4 concentrations in population with metabolic syndrome (male: 29.34 ng/mL, female: 37.00 ng/mL) is significantly higher than that in those without metabolic syndrome (male: 16.63 ng/mL, female: 17.81 ng/mL)." (PMID 31826012, 2019). "Furthermore, body mass index and triglycerides were independent predictors for FABP4 concentration, and this relationship was independent of HD duration, suggesting that a high level of FABP4 is attributable to metabolic syndrome even in patients with ESRD." (PMID 22102888, 2011). "Our recent study using fatty acid-binding protein 4- (Fabp4-) GDF5 transgenic (TG) C57BL/6J mice showed that TG mice developed a relatively lean phenotype on a high-fat diet (HFD), did not develop metabolic syndrome, and demonstrated increased insulin sensitivity." (PMID 33542911, 2021).
type 2 diabetes (125 papers, 2005 to 2025). "In humans, FABP4 haplo-insufficiency is associated with a decreased risk of type 2 diabetes and cardiovascular disease." (PMID 40748030, 2025). "In type 2 diabetes patients, FABP4 levels were positively associated with peripheral artery disease, similar to a study involving hemodialysis patients." (PMID 38698167, 2024). "FABP4 has been implicated in AS, and studies using small-molecule inhibitors of aP2 have demonstrated effective treatment for severe AS and type 2 diabetes in mouse models." (PMID 37645520, 2023). "Most critical to note is that glucose-stimulated insulin secretion (GSIS) from islets of FABP4-deficient animals is enhanced, and these mice are strongly protected against both type 1 and type 2 diabetes." (PMID 37279064, 2023). "This is consistent with recently published data indicating that an elevated FABP4 level is associated with the incidence of type 2 diabetes in humans." (PMID 33068125, 2021). "Actually, increased circulating FABP4 levels were associated with endothelial dysfunction in patients with type 2 diabetes." (PMID 33287461, 2020). "Alleles that reduce FABP4 expression are protective, while those associated with higher levels of FABP4 increase susceptibility to cardiovascular disease and type 2 diabetes." (PMID 32856199, 2020). "While another study performed in type 2 diabetes patients with acute ischemic stroke confirmed that increased level of FABP4 was related to an elevated risk of poor outcomes." (PMID 30969942, 2019). "This study evaluated the association between serum FABP4 and the radioisotope glomerular filtration rate (rGFR) in type 2 diabetic patients (T2DM) with early diabetic nephropathy." (PMID 29992142, 2018). "Because type-2 diabetes is associated with high FABP4 values, a possible link between type-2 diabetes and an increased risk of developing HF cannot be completely excluded." (PMID 23642261, 2013). "Furthermore, multiple prior GWAS studies reported that humans carrying a low-expression variant of FABP4 exhibit significant protection against the development of type 2 diabetes and cardiometabolic disease." (PMID 39843629, 2025). "Another study provided evidence of a large polygenic component to FABP4 protein levels, and genetic correlation analyses shows that variants affecting FABP4 protein levels are also positively correlated with coronary artery disease, type 2 diabetes, waist-hip-ratio, and creatinine." (PMID 38698167, 2024). "Decreasing FABP4 levels is also associated with augmented cardiomyocyte pathology and improved ventricular function in diabetic mouse models, with the increased FABP4 levels seen in type II diabetes potentially the cause of diabetic-induced cardiomyopathy." (PMID 37514127, 2023). "Importantly, multiple independent studies in humans carrying a low-expression variant of FABP4 demonstrated lower incidence of type 2 diabetes, decreased circulating triglycerides and cholesterol, and reduced incidence of cardiometabolic disease." (PMID 37279064, 2023). "Serum fatty acid-binding protein 4 (FABP4), as an intracellular lipid chaperone and adipokine, was reported to be related to the incidence of type 2 diabetes (T2D) and diabetic complications, but its association with pancreatic islet β-cell and α-cell functions has not been fully elucidated." (PMID 34174950, 2021). "High levels of FABP4 were also significantly associated with stroke risk and severity, independent from other risk factors, while elevated serum FABP4 levels were associated with poor prognosis in ischemic stroke patients with type 2 diabetes." (PMID 32075656, 2020). "We also identified seven genes (Sardh, Slc39a7, Pfn1, Arg1, Cth, Sod1 and P4hb) in the liver and one gene (Fabp4) in the adipose tissue that may be associated with type 2 diabetes in gerbils." (PMID 29394254, 2018). "Serum FABP4 levels have been shown to predict the risk of developing both type-2 diabetes and MS." (PMID 23642261, 2013).
type 2 diabetes (continued). "Dysregulated FABP4 expression is implicated in obesity, type 2 diabetes mellitus (T2DM), and cardiovascular disease." (PMID 40871049, 2025). "Subsequently, a rabbit-derived monoclonal anti-FABP4 antibody was developed with a therapeutic effect for treating type 2 diabetes in obese mice." (PMID 39054536, 2024). "This role for hormonal FABP4 has been supported by studies using anti-FABP4 antibodies, which have demonstrated great therapeutic benefit in the treatment of both type 1 and type 2 diabetes in preclinical models." (PMID 37172691, 2023). "Further comparative studies on the role of FABP4 between type 1 and type 2 diabetes are required to elucidate these differences." (PMID 34638803, 2021). "In humans, plasma levels of Fabp4, which is mainly produced by adipocytes, have been positively correlated with cardio-vascular disease, type-II diabetes and also with the progression of other diseases by a still undefined mechanism." (PMID 34409430, 2021). "FABP4 has been reported as a marker protein for type 2 diabetes and a protein target for inflammatory diseases." (PMID 34880765, 2021). "On the other hand, a monotherapy with sitagliptin and combination therapy with sitagliptin and a sulfonylurea agent for 12 weeks significantly decreased FABP4 concentration in patients with type 2 diabetes." (PMID 32539832, 2020). "Recently, it was revealed that FABP4 is an attractive molecular target for the treatment of type 2 diabetes, other metabolic diseases, and some type of cancers." (PMID 31683588, 2019). "The prognostic value of FABP4 in in patients with type 2 diabetes and acute ischemic stroke also had been suggested." (PMID 30969942, 2019). "Previous studies suggest that targeting FABP4 with inhibitors is possible to prevent and treat metabolic diseases, such as type II diabetes and atherosclerosis." (PMID 28808264, 2017). "In a rat model of a rotator cuff tendon associated with persistent type II diabetes, tendons were characterized by the increased expression of tenascin C (TNC) and fatty acid binding protein 4 (FABP4), overall contributing to a significant biomechanical decline of the rotator cuff tendon." (PMID 40001567, 2025). "Other data also suggest FABP4 was higher in type 2 diabetes patients compared to healthy individuals, and may present a biomarker for cardiovascular disease given its association with arterial stiffness, renal function, adiposity, and hypertriglyceridemia." (PMID 38698167, 2024). "Conversely, a large study involving over 27,000 participants shows that FABP4 is associated with risk of type 2 diabetes, and potentially stroke risk, but not with myocardial infarction." (PMID 38698167, 2024). "The FABP4 gene has recently been identified as a common risk factor in a collaborative genome‐wide association study (GWAS) involving 500,000 individuals, focusing on CVD and type 2 diabetes." (PMID 39527497, 2024). "In addition, in patients with end-stage renal disease, as well as in patients with type 2 diabetes, FABP4 levels are predictive of cardiovascular death." (PMID 38698167, 2024). "Fat infiltration-related genes (FABP and PPARγ) expression tended to increase in supraspinatus muscle specimens, and fat infiltration developed gradually over time, with FABP4 mRNA expression levels significantly increasing in the 2-week group after type 2 diabetes induction (p < 0.05)." (PMID 36299460, 2022). "While further studies are still needed to complete FABP4 role in type 1 diabetes and in inflammation, this deleterious adipose-derived lipid-binding protein may be a new target to treat type 2 diabetes." (PMID 34638803, 2021). "We have recently reported that the circulating levels of the fatty acid binding protein 4 (FABP4), reflects the myocardial neutral lipid content in type 2 diabetic patients, thus proposing this molecule as an emerging biomarker for ectopic fat deposition in non-adipose tissues." (PMID 34966292, 2021).
type 2 diabetes (continued). "Previously, it has been reported that circulating FABP4 may be a potential biomarker for the progression of nephropathy in type 2 diabetic patients." (PMID 32887447, 2020). "FABP4 suppresses contraction of cardiomyocytes in a rodent model and FABP4 might increase intracellular lipid accumulation in patients with type 2 diabetes leading to myocardial dysfunction." (PMID 32727561, 2020). "Moreover, FABP4 plasma concentrations have been reported to potentially be an early clinical marker of renal function derangement in patients with type 2 diabetes." (PMID 31234795, 2019). "Similarly, a long-term prognostic role of FABP4 in patients with coronary heart disease was proposed, while circulating FABP4 levels were reported to be an independent biomarker of various mortality in type 2 diabetes." (PMID 32075656, 2020). "Studies have shown that FABP4 knockout mice were protected from diseases such as atherosclerosis and the type 2 diabetes mellitus (T2DM; Furuhashi and Hotamisligil, 2008)." (PMID 30364164, 2018). "Korean red ginseng, other traditional herbal medicine used to prevent several geriatric diseases due to its therapeutic effects on metabolic disorder (i.e., type 2 diabetes and fatty liver disease), improved MASH-related inflammation by reducing both FABP4 mRNA and protein levels." (PMID 35052876, 2022). "Gastric bypass surgery reduces circulating FABP4 by 42% in obese patients with type 2 diabetes, whereas behavioral and nutritional intervention alone does not reduce the serum levels of FABP4." (PMID 34638803, 2021). "FABP4 concentrations were up-regulated in culture supernatants of MNCs from CAD patients, which were positively correlated with the patients’ age, waist–hip ratio, body mass index, serum creatinine, type 2 diabetes, and the presence of hypertension." (PMID 33287461, 2020).
breast cancer (110 papers, 2008 to 2025). A primary or metastatic malignant neoplasm involving the breast. "Obese people with breast cancer have been found to have higher levels of FABP4, which is associated with aggressiveness and stemness in breast cancer." (PMID 39858015, 2025). "Fabp4, a circulating fatty acid-binding adipokine, is linked to mammary tumour progression and milk yield in dairy cows." (PMID 40925719, 2025). "In breast cancer, FABP4 expression and function are linked to the tumor microenvironment and cancer progression." (PMID 40870889, 2025). "have reported a significant upregulation of SCD1 and fatty acid-binding protein 4 (FABP4) in human breast cancer specimens, which is associated with poor prognosis in different types of breast cancer." (PMID 39664391, 2024). "After evaluating the efficacy of its chimeric version and humanized variants, we successfully generated a humanized FABP4 monoclonal antibody (mAb), which offers potential for treating breast cancer in the clinic." (PMID 39054536, 2024). "Collectively, CD163+ TAMs, especially those with FABP4 expression, are positively associated with tumor growth and metastasis in breast cancer patients." (PMID 39513934, 2024). "Inhibition of CD36 and FABP4 significantly reduces the proliferation, migration, invasiveness, and tumorsphere-forming capacity of breast cancer cells, which is associated with reduced tumorigenicity in a xenograft mouse model." (PMID 38060103, 2023). "Especially, overexpression of FABP4 in tumor-associated macrophages promotes breast cancer growth, and blocking FABP4 expression in endothelial cells reduces angiogenic activity and tumor growth." (PMID 36264920, 2022). "The expression of an additional extrinsic factor, obesity-associated fatty acid binding protein 4 (FABP4), is elevated in patients with breast cancer." (PMID 34202411, 2021). "An increased circulating level of FABP4 has been reported in obese breast cancer patients and associated with breast cancer stemness and aggressiveness." (PMID 34359819, 2021). "Moreover, FABP4 has been implicated in promoting angiogenesis, a critical process for the establishment and progression of solid tumors, including breast cancer." (PMID 40870889, 2025). "Our current evidence suggests that targeting FABP4 with humanized monoclonal antibodies may represent a novel strategy for the treatment of breast cancer and possibly other obesity- associated diseases." (PMID 39054536, 2024). "High expression of FABP4 in TAMs is associated with more metastasis of breast cancer." (PMID 39513934, 2024). "Additionally, obese patients with breast cancer displayed significantly higher FABP4 levels in serum, which were associated with larger tumor size and poorer prognosis, regardless of menopausal status." (PMID 36060264, 2022). "FABP5 is linked to breast cancer proliferation and resistance, whereas serum and tumor FABP4 levels were found to be significantly higher in BC patients than that of healthy controls and were positively connected with tumor size, aggressiveness and lymph node involvement." (PMID 31941087, 2020). "In colorectal and breast cancers, overexpression of FABP4 and FABP5 has been correlated with recurrence risk and chemoresistance, suggesting their utility in identifying high-risk patients who may benefit from intensified adjuvant treatment or early postoperative monitoring strategies." (PMID 40717587, 2025). "Similarly, other downregulated genes (Fabp4, Mrc1, Lpl, Cd209d, and Cd209a) were also found to be involved in breast cancer and may be associated with bone metastases." (PMID 35388653, 2022). "Therefore, it is safe to assume that the previous controversy over the association between BMI and breast cancer prognosis maybe related to the distribution difference of the FABP4 genotype among different populations." (PMID 26959740, 2016).